BRCA1 (BRCA1 DNA repair associated)
Diseases named in the same sentence as BRCA1 in open-access papers (continued):
Sharing a sentence is not in itself a finding about the gene and the disease.
breast cancer (continued). "Consequently, the present study aimed to investigate imaging features of breast cancer developing in Japanese BRCA1/2 mutation carriers to build a proper surveillance system for asymptomatic high-risk individuals in the future." (PMID 30820924, 2019). "Moreover, LST score, mutational signature 3, NtAI score and Myriad score detected bi-allelic inactivation of PALB2 and of BRCA1/BRCA2 in PALB2-associated breast cancers and in BRCA1/2-associated breast cancers, respectively, with comparable accuracy." (PMID 31428676, 2019). "Moreover, increased ROS levels have been associated with BRCA1 mutations in this type of breast cancer." (PMID 31231612, 2019). "New PR-regulated genes and pathways were discovered that provide a broader perspective of how hormones, with BRCA1 mutations, could increase risk of breast cancer." (PMID 31771627, 2019). "The conclusions of this study suggested that BRCA1 mutation in TH patients may drive the clinical TH phenotype (based on elevated ovarian cancer risk and earlier age of breast cancer diagnosis vs subjects carrying a single pathogenic variant in BRCA2)." (PMID 31336956, 2019). "Interestingly, studies of breast cancer models with a BRCA1 mutation show increased insertion-deletion (in-del) mutations at BRCA1-bound termination sites known to inhabit R-loops." (PMID 31225499, 2019). "Regarding the difference found in the family history of women with mutations in BRCA1 or BRCA2 genes, we can observe that BRCA1 mutated families showed a higher frequency of bilateral breast cancer (OR=4.96 vs. OR=1.67) and presence of ovarian cancer (OR=4.32 vs. OR=1.63)." (PMID 31244284, 2019). "Thus, in patients with breast carcinomas who are younger than 40 years old with genetic risk factors, the BRCA1/2 mutation prevalence was 19.5%." (PMID 30713775, 2019). "Although fibroadenoma might have the potential to develop into invasive in situ carcinoma in women with the BRCA1 gene mutation, the overall risk of fibroadenoma progression to breast carcinoma is very low." (PMID 30744493, 2019). "Similarly, patient 12 (NTM-BCa-12) with a history of alcohol consumption who was diagnosed with NTM (MAC) at age 55 and stage-IB breast cancer at age 61 exhibited numerous somatic and germ line BRCA1 and BRCA2 mutations in the sputum." (PMID 30054559, 2018). "Hence, screening of germline BRCA1/2 mutations is crucial for appropriate clinical management of cancer risk, yet more studies on the prevalence and cumulative breast cancer risk for these genes in Asian women are warranted." (PMID 29861850, 2018). "In addition, and considering similarities in the population analyzed, this study presents a comparison with results previously published by our group on BRCA1/2 mutations in breast cancer patients." (PMID 30103829, 2018). "Arguably, CHEK2 is one of the most important breast cancer susceptibility genes after BRCA1/BRCA2." (PMID 30257646, 2018). "Taken together, these findings suggest that BRCA1-associated lacrimal gland tumors share molecular characteristics with BRCA1-deficient breast cancer and that structural proteins exhibit the alteration in level and distributions depend on the progression of cancer." (PMID 30652068, 2018). "Second, olaparib exposure was shown to increase PD-L1 expression in BRCA1/2-mutated breast cancer cell lines or xenograft, which was associated with inhibition of T lymphocyte cytotoxicity, whereas combining olaparib with a monoclonal anti-PD1 revealed to be synergistic." (PMID 30544963, 2018). "For example, the poly(ADP-ribose) polymerase (PARP) inhibitor olaparib induces enhanced cytotoxicity in breast cancer cells that harbor BRCA1/2 mutations, as their endogenous DNA damage repair systems are suppressed by both BRCA1 inactivation and PARP inhibition." (PMID 29565815, 2018). "Investigating the correlation of the changes in the plasma telomeric cfDNA level with specific BRCA1&2 mutation sites may provide new insights into risk assessments of breast cancer." (PMID 29423116, 2018).
breast cancer (continued). "Recent evidence from prospective cohort studies suggests that women at high risk for breast cancer based on their family history or genetic testing, including BRCA1/2 mutation carriers, benefit from screening that includes magnetic resonance imaging (MRI) in addition to mammography." (PMID 29368425, 2018). "Moreover, in a separate study, we identified rs16942-BRCA1 as a modifier variant of breast cancer risk in BRCA1 mutation carriers." (PMID 30594178, 2018). "However, BRCA2 carriers appear unaffected by SNPs that confer an increased breast cancer risk in BRCA1 carriers, even though both genes play a role in homologous recombination." (PMID 29147930, 2018). "Furthermore, the maternal aunt and the maternal grandmother, both obligate carriers for the BRCA1 variant, developed an ovarian cancer at the age of 59 and a breast cancer at 70, respectively." (PMID 29346284, 2018). "Considering this strategy, we also provided evidence that modulating mitotic progression and cyclin B1 expression could be therapeutically beneficial in the treatment of BRCA1-associated breast cancer." (PMID 30327455, 2018). "Within a breast cancer biobank research study, ten germline mutations in BRCA1 (n = 5) or BRCA2 (n = 5) were incidentally revealed in study participants that were themselves not aware of their mutation carrier status, 5–7 years after they had been included in the study." (PMID 29082482, 2018). "Among the intrinsic subtypes of BRCA1-associated breast cancers, 75.8% were triple-negative." (PMID 29176636, 2018). "However, this is 10 years older than in the American population, in which the average age of breast cancer diagnosis in BRCA1/2 pathogenic mutation carriers is 41 years." (PMID 30040829, 2018). "In summary these results demonstrate that transplantation of representative p18−/−;Brca1MGKO and p16−/−;Brca1MGKO tumor cells into MFPs of NSG mice generate reproducible ER-negative tumors, which build a model system to study BRCA1-deficient mammary tumor development and progression." (PMID 29996906, 2018). "In breast cancer, a single pathogenic BRCA1/2 variant can reach a penetrance of more than 50%." (PMID 29719599, 2018). "The incidence of breast cancer in unaffected BRCA1/2 mutation carriers was 3.8%/year." (PMID 29176636, 2018). "From the first part of the study we could substantiate the role of CAFs in inducing the metastatic ability exploiting the BRCA1 deficiency in breast cancer cells." (PMID 30224826, 2018). "BRCA1/2 associated breast cancers have been known to respond better to platinum based chemotherapy." (PMID 29433453, 2018). "The risk of breast cancer in the first-degree relatives of BRCA1 and BRCA2 probands was significantly higher than in first-degree relatives of non-carrier families (hazard ratio, HR=3.31, 95% CI 2.46-4.44, p<0.001; HR=3.31, 95% CI 2.46-4.44, p<0.001 for BRCA1 and BRCA2 respectively)." (PMID 29861850, 2018). "Thus, more than 80% of BRCA1-associated breast cancer correspond to triple-negative breast cancer (TNBCs)." (PMID 30544963, 2018). "As carriers may increasingly undergo IVF as part of preimplantation genetic diagnosis (PGD), we examined the impact of ovarian stimulation for IVF on breast cancer risk in BRCA1/2 mutation carriers." (PMID 29937543, 2018). "Breast cancer xenografts using HCC1935 with mutated BRCA1 showed complete inhibition of tumor growth upon treatment with cisplatin whereas only partial response in xenografts that had the wild-type BRCA1 reconstituted." (PMID 29459887, 2018). "It seems that the decrease in BRCA1 expression, whether due to germline mutations in hereditary breast cancers or hypermethylation in sporadic breast cancers, could increase the risk of breast cancer in women at younger ages." (PMID 28646826, 2018).
breast cancer (continued). "Furthermore, DNA hypermethylation results in aberrant regulation of the Wnt pathway in breast cancer, and BRCA1 expression is suppressed by a combination of gene mutation and DNA hypermethylation." (PMID 30249004, 2018). "BRCA1 mutation carriers with breast cancer may benefit from treatment with oophorectomy, cisplatinum, or olaparib compared to those without a mutation." (PMID 30572612, 2018). "Mutations mostcommonly associated with breast cancer affect BRCA1 andBRCA2; mutations in several other genes may also conferbreast cancer risk." (PMID 30241137, 2018). "In breast cancer, germline mutations in BRCA1 and BRCA2 genes may support the carcinogenic process in around 20% of the young patients, but only in 1-4% of post-menopausal women." (PMID 29854292, 2018). "BRCA1 mutation testing may be useful in clinically sporadic breast cancer patients with medullary features to identify potential mutation carriers independently from intrinsic molecular subtype." (PMID 29453630, 2018). "Determining BRCA1/2 mutation status in this breast cancer subgroup could potentially expand treatment options beyond the current standard of taxane and anthracycline-based chemotherapy." (PMID 29867226, 2018). "The majority of BRCA1 mutated breast cancers are so-called “triple negative” or of “basal-type”." (PMID 29453630, 2018). "In summary, our results support the conclusion that BRCA1/2 mutations are common among Jordanian breast cancer patients with a highly selected risk profile and may contribute to the pathogenesis of disease in this patient population." (PMID 29409476, 2018). "The incidence rate of contralateral breast cancer in BRCA1/2 mutation carriers was 0.99%/year." (PMID 29176636, 2018). "This study not only reveals the molecular mechanisms underlying the role of estrogen in promoting development and progression of ER-negative basal-like breast cancers but also identifies a druggable AKT pathway that is activated by estrogen in BRCA1-deficient breast cancers." (PMID 29996906, 2018). "The proband’s asymptomatic 91-year-old mother (II.9) bore only the mutation in BRCA1 in a similar fashion to the sister with breast cancer who died at 56 years of age (III.3), and for whom the analysis was performed on formalin-fixed, paraffin-embedded (FFPE) tissue." (PMID 29346284, 2018). "The gene that contributed most to risk was BRCA1, both because 7.0% of patients (80 of 1,136) harbored a damaging mutation in BRCA1 and because the increase in breast cancer risk associated with BRCA1 mutation was extremely high (OR, 23.40; 95% CI, 7.41 to 73.88; P < .001)." (PMID 30130155, 2018). "We urge inhibiting β‐hCG could prove an effective treatment strategy for BRCA1 mutated breast cancers." (PMID 29460395, 2018). "Higher BARD1 and BRCA1 expression is associated with worse prognosis of early breast cancer patients, especially the ones that received radiotherapy, indicating the potential use of PI3K inhibitors to reverse chemoresistance and radioresistance in ER-positive breast cancer patients." (PMID 29686231, 2018). "Furthermore, we also used a PTV-ALFRED model to analyze each of the 17 cancer types and three genes were significant in at least one individual cancer type (FDR = 0.2, four associations: BRCA2 and ATM in breast cancer, BRCA1 and BRCA2 in ovarian cancer)." (PMID 29973584, 2018). "BRCA1-185 Del AG mutation has association with early age onset of breast cancer." (PMID 30344568, 2018). "Interestingly, although BRCA1 mutant breast cancers are often categorized as HR-deficient, at least one BRCA1 mutation can lead to genetic instability via excessive resection of DNA breaks and hyper-recombination." (PMID 30333500, 2018).
breast cancer (continued). "In addition, its dysfunctional mutated status has been identified in BRCA1-mutated, PARPi-resistant, murine breast-cancer models." (PMID 30347758, 2018). "Our specific aims were to examine the level of methylation of important breast cancer genes in a series of MBC cases all characterized for BRCA1/2 mutation status and to identify potential molecular subgroups defined by their methylation patterns with clinical-pathologic correlation." (PMID 29731982, 2018). "Importantly, we demonstrated that estrogen activates EMT in a subset of ER-negative and Brca1-deficient mammary tumor cells, promoting their properties in tumor initiation and progression." (PMID 29996906, 2018). "Similarly, whole-exome sequencing, RNA sequencing and DNA copy-number-based approaches have identified several driver genes in mouse models of Brca1- and Brca2-deficient breast cancer." (PMID 30111589, 2018). "Indeed, HGSOC with diminished BRCA1 or BRCA2 expression typically have increased sensitivity to DNA damaging chemotherapeutics and restoration of BRCA1 in a BRCA1 deficient breast cancer cell line decreased cisplatin sensitivity in a xenograph model." (PMID 29973223, 2018). "A meta-analysis of cumulative risks for contralateral breast cancer in BRCA1/2 mutation carriers with a first breast cancer showed a cumulative 10-year incidence rate of 27% and 19% for contralateral breast cancer in BRCA1 and BRCA2 mutation carriers, respectively." (PMID 29176636, 2018). "The results obtained in the current study using this mouse simulation system suggest that targeting of mitosis and cyclin B1 could be a useful strategy for treating BRCA1-associated breast cancer." (PMID 30327455, 2018). "Alkylating agents are mechanistically related to platinum compounds, but their specific impact in breast cancer patients with BRCA1/2 germline mutation remains unclear." (PMID 30544963, 2018). "Interestingly, the overall mutation frequency of BRCA1/2 decreases with age in breast cancer patients, suggesting that deleterious mutations in BRCA1/2 are found in earlier-onset cancers." (PMID 30551670, 2018). "Furthermore, there is a common shared etiology for ER-negative breast cancer and breast cancers arising in BRCA1 mutation carriers as well as overall breast cancer and breast cancer in BRCA2 mutation carriers." (PMID 30116257, 2018). "Response rate and PFS were significantly lower in patients carrying BRCA1 mutations (23% versus 38%, p < 0.001 and 2.2 months versus 4.9 months, p = 0.04) compared to sporadic breast cancers, most of the difference being driven by hormone receptor-negative tumors." (PMID 30544963, 2018). "We analyzed BRCA1/2 mutation status in 32 breast cancer patients with medullary features." (PMID 29453630, 2018). "Indeed, comparable studies in BRCA1 or BRCA2 mutation carriers have resulted in the identification of SNPs that clearly modify breast cancer risk." (PMID 29147930, 2018). "Poly(adenosine diphosphate [ADP]-ribose) polymerase (PARP) inhibitors have shown an impressive safety profile and anti-tumor efficacy in patients with breast cancer 1 and 2 (BRCA1 and BRCA2) gene-mutated ovarian cancer who were previously treated with the standard of care chemotherapy." (PMID 30050740, 2018). "In addition, to increase the potential clinical efficacy of vinblastine against BRCA1-deficient breast cancer, we also sought to identify specific efficacy-associated genes by examining gene expression patterns in untreated tumors." (PMID 30327455, 2018). "Therefore, this study contributes to improved identification of patients with a pathogenic variant, especially in genes other than BRCA1/2, in the diagnosis of hereditary breast cancer in clinical practice in Japan." (PMID 30287823, 2018).
breast cancer (continued). "Considering the current limitations in available treatment options for BRCA1-associated breast cancer, preclinical simulation in a mouse model, such as our approach using Brca1-mutant mice bearing endogenous tumors, will remain a useful strategy for testing treatment efficacy." (PMID 30327455, 2018). "The high proportion of hormone receptor positive cases might possibly reflect the histological variability of medullary differentiation in breast cancer and might also contribute to the low frequency of somatic BRCA1 mutations." (PMID 29453630, 2018). "According to two small prospective studies with relatively short follow-up, women with BRCA1 or BRCA2 mutations may benefit from a significant reduction in breast cancer risk following bilateral total mastectomy." (PMID 29713580, 2018). "In contrast, a recent meta-analysis demonstrated a (not statistically significant) trend towards increased risk of breast cancer under contraceptive use in both BRCA1 (OR = 1.19; 95% CI, 0.92–1.55) and BRCA2 carriers (OR = 1.21; 95% CI, 0.93–1.58) compared to the general population (OR≈1.08) [58•]." (PMID 30363743, 2018). "Indeed, prophylactic bilateral salpingo-oophorectomy from 35 years of age and prophylactic bilateral mastectomy in BRCA1 carriers reduce the risk of developing breast cancer by 50% and by more than 90%, respectively, although this has been recently challenged." (PMID 29996917, 2018). "In a recent meta-analysis of the literature, tamoxifen use for the treatment of a first breast cancer resulted in a significant 44% risk reduction of a second breast cancer in both BRCA1 and BRCA2 mutation-positive patients combined (summary HR = 0.56; 95% CI 0.41–0.76)." (PMID 30572612, 2018). "Women carrying a pathogenic variant (PV) in the BRCA1 or BRCA2 (BRCA1/2) genes are at high lifetime risk of developing breast cancer (BC) and ovarian cancer (OC), but estimation of the cumulative risk of cancer to age 70 years varies substantially between studies and populations." (PMID 30430080, 2018). "Our findings also suggest that high-risk breast cancers, particularly for Asians, might consist of multiple layers with similar importance, including BRCA1/2, moderate/high-penetration genes, and selected common variants with augmented effects." (PMID 30323354, 2018). "However, one must take into consideration that breast cancer in BRCA1 mutation carriers develops at a significantly younger age, about 10 years younger than sporadic breast cancer." (PMID 30174725, 2018). "Moreover, low XRCC1 expression has recently been reported to impact prognosis in BRCA1-deficient breast cancers." (PMID 29568385, 2018). "However, though TNBCs constitute nearly 80% of BRCA1-associated breast cancers, BRCA1 mutations have only been found in a subset of TNBC patients." (PMID 30257646, 2018). "Among the other patients’ risk groups recruited to the study, 2 out of five (40.0%) patients with family history of male breast cancer and 10 out of 15 (66.7%) patients with bilateral or second primary breast cancer reported deleterious/suspected deleterious BRCA1/2 mutations." (PMID 29409476, 2018). "Platinum agents also showed efficacy for BRCA1 mutation carriers with advanced breast cancer." (PMID 29719582, 2018). "The incidence rate of breast cancer is 3.8%/year in unaffected BRCA1/2 mutation carriers." (PMID 29176636, 2018). "In total, 938 BRCA1/2 mutation carriers (37.3%) were diagnosed with breast cancer." (PMID 29937543, 2018). "This review will address recent clinical evidences supporting the role of these treatments, as well as other cytotoxics in BRCA1/2-associated breast cancer, and will examine how novel emerging strategies may be built on these promising results." (PMID 30544963, 2018).